RPL7P61 (ribosomal protein L7 pseudogene 61)
Gene: Processed pseudogene on chromosome 2 (163,152,251 to 163,153,307, reverse strand). Ensembl gene ENSG00000230282.
Diseases named in the same sentence as RPL7P61 in open-access papers:
RPL7P61 is named in the same sentence as 1 disease in open-access papers, as found by Europe PMC text mining. Sharing a sentence is not in itself a finding about the gene and the disease. The quoted sentences say what the papers report.
breast carcinoma (1 paper, 2017). "Prior genome-wide association studies have identified variants in RPL7P61 as associated with phospholipid levels as well as breast cancer survival." (PMID 28820441, 2017).